INS (insulin)
Diseases named in the same sentence as INS in open-access papers (continued):
Sharing a sentence is not in itself a finding about the gene and the disease.
COVID-19 (continued). "In other studies, metformin, sulfonylurea, and sodium-glucose Cotransporter-2 Inhibitors decreased mortality risk, but insulin therapy and gliptins are linked with a high risk of severe outcome and mortality in COVID-19." (PMID 36983573, 2023). "Literature data show that insulin treatment would be linked with adverse outcomes in diabetic patients with COVID-19." (PMID 36983573, 2023). "As an ACSL4 inhibitor, TZDs not only interrupt the oxidation of AA or AdA to reduce the pathological damage caused by COVID-19 but also acts as an insulin sensitizer." (PMID 37303950, 2023). "Agonist-dependent SARS-CoV-2 sgRNA expression was investigated using agents associated with COVID-19 severity and outcome, i.e., insulin and interferon (IFN)-γ." (PMID 37296097, 2023). "The underlying cause of glucose imbalance in COVID-19 patients is complex and multi-dimensional, encompassing insulin resistance and β-cell dysfunction." (PMID 37511334, 2023). "Previous studies have shown that preadmission insulin treatment was associated with a higher risk of COVID-19-related death, while preadmission metformin treatment lowered that risk." (PMID 36844106, 2023). "COVID-19 patients with new or worsened glucose dysregulation requiring additional or new insulin administration were associated with poorer outcomes in a study of 456 patients." (PMID 37759668, 2023). "In fact, it was observed that patients treated with metformin had a less severe form of COVID-19 and a reduced risk of mortality compared to patients treated with insulin." (PMID 36677437, 2023). "In this context, the assessment of anthropometric and metabolic parameters, including BMI, waist and hip circumferences and glucose and insulin levels, is crucial to estimate the risk of complications in patients with COVID-19." (PMID 35631195, 2022). "Evidence on the occurrence of complications associated with COVID-19 in pregnant patients with GDM treated with insulin is limited." (PMID 36079820, 2022). "Some strains of Akkermansia (phylum Verrucomicrobia) were associated with lower insulin sensitivity; A. muciniphila was detected in COVID-19 patients during hospitalization." (PMID 36142219, 2022). "Type 1 diabetes (T1D), which is caused by the autoimmune destruction of insulin-secreting pancreatic beta cells, represents a high-risk category requiring COVID-19 vaccine prioritization." (PMID 35891261, 2022). "The MR analyses however found less compelling evidence that central fat distribution, insulin resistance or other markers of metabolic disturbance from excess adiposity were casually associated with COVID-19 outcomes." (PMID 35031696, 2022). "Therapy with metformin, DPP-4 inhibitors, SGLT2 inhibitors, arGLP-1 before the infection and anti-COVID-19 vaccination were associated with a lower CFR, while SU and insulin therapy was associated with a higher CFR due to COVID-19." (PMID 36017317, 2022). "A retrospective study involving 689 T2DM patients with COVID-19 reported that insulin therapy is significantly associated with increased mortality, accompanied by aggravated systemic inflammation and exacerbated damage to vital organs." (PMID 34867819, 2021). "Insulin treatment was significantly associated with an increased risk of mortality (OR=2.10; 95% CI, 1.51-2.93) and incidence of severe/critical COVID-19 complications (OR=2.56; 95% CI, 1.18-5.55)." (PMID 34367067, 2021). "Description of studies reporting the association between insulin treatment and the severe/critical complications or in-hospital admission of COVID-19." (PMID 34367067, 2021). "Third, the causal relationship between insulin treatment and COVID-19 outcomes remains vague due to the limited amount of prospective data in our included studies." (PMID 34367067, 2021). "Only 2 studies mentioned the association between insulin treatment and COVID-19 hospitalization time (SMD=0.21 95% CI, -0.02-0.45)." (PMID 34367067, 2021).
COVID-19 (continued). "Related to risk factors associated with COVID-19, a reduction in PA results in reduced mitochondrial oxidative capacity and insulin signaling in human skeletal muscle." (PMID 34564326, 2021). "In general, the use of insulin is associated with increased mortality due to COVID-19 (OR=2.10 95% CI, 1.51-2.93); high heterogeneity was observed (I2 statistic=71.5%, p<0.001)." (PMID 34367067, 2021). "In summary, our study revealed that insulin treatment is associated with increased mortality and other severe/critical complications of COVID-19." (PMID 34367067, 2021). "Limitations to their use associated with corticosteroid-mediated inhibition of glucose uptake and reductions in insulin sensitivity in COVID-19 patients and their role in increasing the susceptibility to acquire other infections are among the major concerns." (PMID 35095801, 2021). "Regarding glucose-lowering medication, chronic insulin use was associated with higher risk of COVID-19-related death, while metformin use was associated with lower risk." (PMID 33907860, 2021). "Still, epidemiological data supporting the idea that COVID-19 leads to new onset of insulin-deficient diabetes are limited." (PMID 34241597, 2021). "In patients with COVID-19 and severe hypoxemia, we found that allocation to higher vs. standard dose dexamethasone was associated with a higher incidence of severe hyperglycemic events despite use of insulin." (PMID 40665171, 2025). "Third, insulin use has been linked to unfavorable outcomes in COVID-19 patients." (PMID 40046873, 2025). "Furthermore, older age, being male, poor glycaemic control, and use of insulin were all independently associated with an increased likelihood of COVID-19 death and hospitalisation in PWDM." (PMID 38976666, 2024). "Moreover, old age, prolong hospitalization, high potassium and lactate dehydrogenase, as well as using insulin, heparin, corticosteroids, favipiravir or azithromycin were all significantly associated with severe COVID-19." (PMID 39895823, 2024). "Thus, our findings showed that poor glycemic control or the use of insulin analogs instead of human insulin increased the risk of PCS development in T2D patients after COVID-19." (PMID 39722811, 2024). "Our study showed insulin was a risk factor for COVID-19 hospitalization and death outcomes." (PMID 38538694, 2024). "Insulin therapy was also associated with increased COVID-19 death risk." (PMID 38538694, 2024). "However, Accili argued that diabetic ketoacidosis after COVID-19 should require conventional insulin therapy if the virus causes permanent loss of β-cell function, but the challenge in clinical practice is mainly extrinsic to the β-cells." (PMID 37304092, 2023). "IR is associated with hypermetabolism during the acute state of COVID-19 as a stress response and increased drive of counterregulatory hormones (such as catecholamines and cortisol) resulting in a decline in both skeletal muscle and liver insulin sensitivity." (PMID 37460458, 2023). "There was high certainty of evidence that insulin use was related to a 33% increased risk of COVID-19-related death (SRR 1.33 [95% CI 1.18, 1.49], n=26 studies), while metformin use was associated with a 31% decreased risk (SRR 0.69 [95% CI 0.60, 0.79], n=23 studies)." (PMID 37204441, 2023). "Another hypothesis is that insulin may increase the susceptibility to lung inflammation and hence may worsen the pulmonary complications associated with COVID-19." (PMID 36079820, 2022). "According to the available data, we found out olfactory training, topical or oral corticosteroids, caffeine, insulin, or minocycline may effectively treat COVID-19 odor loss." (PMID 36407192, 2022). "Indeed, the so-called ‘cytokines storm’ scenario resulting from severe COVID-19 is associated not only with an enhancement of insulin-resistance situation but also with impaired insulin production from the pancreatic β cells." (PMID 36619546, 2022).
COVID-19 (continued). "Maybe both; insulin treatment is associated with a significant increase in the death rate in patients with COVID-19 and T2D." (PMID 35723340, 2022). "Patients with GDM and insulin treatment should be considered high-risk patients, especially when characterized by a high BMI, and should be monitored closely, as this population has been shown to be affected more often by severe COVID-19." (PMID 36079820, 2022). "In the current study, if insulin is properly adjusted and its action boosted, its association with IL-6 may turn out to be a beneficial routine for critically ill and diabetic COVID-19 patients." (PMID 35530861, 2022). "Therefore, it is plausible that pregnancies treated with metformin instead of insulin are at a lower risk of adverse outcomes and COVID-19-related mortality." (PMID 36079820, 2022). "Several studies have shown that insulin therapy was linked to poor prognosis in COVID-19." (PMID 34031865, 2021). "Insulin use tended to be associated with greater mortality in patients with COVID-19." (PMID 34603199, 2021). "Therefore, we conducted a systematic review and meta-analysis to determine the association between insulin injection and the outcomes of COVID-19 to provide certain clinical information for these patients." (PMID 34367067, 2021). "Interestingly, in diabetic COVID-19 patients, while insulin administration was associated with adverse outcomes, Metformin treatment was correlated with a significant reduction in disease severity and mortality rates among affected individuals." (PMID 34157054, 2021). "Furthermore, a substantial decrease in doctor visits was observed in women, and large to moderate reductions were seen in patients who take insulin and are of advanced age, who are at high risk of developing severe COVID-19." (PMID 34841037, 2021). "Although the mechanism underlying the association between insulin use and the poor outcome of COVID-19 remains unclear, there are several possible explanations for these results." (PMID 34367067, 2021). "In addition, several pathways, including those associated to the response to glucose and insulin pathways, were enriched by the DEGs in COVID-19 and DM, as observed in the pancreas-related transcriptomic profiles." (PMID 34260684, 2021). "Additionally, insulin was associated with increased lung inflammation in a sepsis model of diabetic rats, while lung cells are the main locations for COVID-19 inflammation." (PMID 34367067, 2021). "The cytokine storm in COVID-19 may induce insulin resistance and directly cause beta cell damage and this may lead to worsening dysglycemia in patient of DM having contracted COVID-19 infection." (PMID 32874422, 2020). "We showed that SARS-CoV-2-encoded miRNAs can target the insulin-signaling pathway, and aberration of this pathway might overcomplicate the whole disease condition for COVID-19 patients with existing diabetic problems." (PMID 32765592, 2020). "However, a recent study examining the effects of insulin therapy in hospitalized diabetic patients with COVID-19 reported a greater than threefold risk of mortality and severe outcome in treated patients." (PMID 33335527, 2020). "Furthermore, if an association between insulin sensitivity and COVID-19 severity is found, consideration should be given to assessing therapeutic interventions to enhance insulin sensitivity and improve outcomes." (PMID 32574288, 2020). "Similarly, it is unclear whether insulin, diuretics and antiplatelets are true risk factors for severe COVID-19 in our population, or whether they are indicators of more severe underlying comorbid conditions." (PMID 38186903, 2024). "One hypothesis is that insulin may increase the levels of proinflammatory cytokine from activated macrophages and promote a proinflammatory state, which may exacerbate the inflammation cascade caused by COVID-19." (PMID 36079820, 2022).
COVID-19 (continued). "However, considering the limited number of studies concerning type 1 diabetes (T1DM) in our meta-analysis, the association between insulin treatment and adverse outcomes in patients with COVID-19 and T1DM are needed to be investigated in more large-scale clinical studies." (PMID 34367067, 2021). "Antibodies against severe acute respiratory syndrome coronavirus 2 (SARS-CoV-2) infection may cross-react or interfere with the functioning of endogenous insulin." (PMID 33154847, 2020). "Aging, Western diets, and COVID-19 significantly exacerbate metabolic reprogramming through shared mechanisms such as insulin resistance, inflammation, and oxidative stress, thereby promoting the onset and progression of CVD." (PMID 40513070, 2025). "Compared to uninfected controls, hospitalized COVID-19 patients exhibited significantly elevated fasting insulin levels, C-peptide, and HOMA-IR." (PMID 40564201, 2025). "This can lead to a disruption in insulin production and secretion, contributing to the metabolic disturbances observed in individuals with COVID-19." (PMID 40048451, 2025). "There is also strong evidence of the protective role of MET against COVID-19 compared to insulin and TZD." (PMID 40650107, 2025). "Conversely, the top downregulated pathways encompass Coronavirus disease − COVID-19, insulin resistance, Notch signaling, the polycomb repressive complex, and ribosomal functions." (PMID 40660393, 2025). "Some authors suggested that COVID-19 promoted deleterious metabolic adjustments in DM patients and that physical activity followed by exercise would have beneficial effects on insulin sensitivity and lipid metabolism homeostasis." (PMID 40469441, 2025). "Persistent low-grade inflammation, dysregulation of the renin–angiotensin system, insulin resistance, and increased tissue stiffness in these patients can lead to an overexpression of pro-inflammatory cytokines in response to COVID-19." (PMID 40283075, 2025). "Pro-inflammatory cytokines released during the immune response disrupt insulin signaling, while corticosteroids used in COVID-19 treatments increase blood glucose by reducing insulin sensitivity." (PMID 40075801, 2025). "Elevated insulin levels can exacerbate inflammation, contributing to the cytokine storm observed in severe COVID-19 cases." (PMID 40136608, 2025). "Autopsy samples from COVID-19 patients demonstrated a reduction in insulin expression and the abnormal presence of trypsin/insulin double-positive cells, confirming that SARS-CoV-2 induces such transdifferentiation of beta cells." (PMID 40469441, 2025). "While dexamethasone has been shown to improve survival in COVID-19, its dose–response relationship with plasma glucose (PG) levels and insulin requirements is poorly understood." (PMID 40665171, 2025). "Firstly, insulin treatment in COVID-19 patients resulted in a significantly higher mortality rate and COVID-19 complications." (PMID 38651404, 2024). "With regard to colostrum, adiponectin, resistin, and insulin concentrations showed an increase in the COVID-19 group (p < 0.01, p < 0.01, and p < 0.05, respectively) compared with the control group." (PMID 38610889, 2024). "COVID-19 impacts the insulin system by targeting, in part, the insulin-like growth factors (IGFs), as they utilize the same class of receptor tyrosine kinases (RTKs)." (PMID 39502570, 2024). "For example, the autopsy of COVID-19 cases showed that SARS-CoV-2 caused the transdifferentiation of pancreatic beta-cells into alpha and acinar cells, resulting in reduced insulin secretion." (PMID 39358227, 2024). "Continuous insulin infusion has been reported to provide rapid TG levels lowering in mechanically ventilated COVID-19 patients." (PMID 38449886, 2024). "In human, insulin nasal spray has also been reported to be effective against COVID-19-induced olfactory dysfunction." (PMID 38903957, 2024).
COVID-19 (continued). "Treatment with insulin, antiplatelets and PPI were associated with increased risk of COVID-19-related mortality (aOR 1.41, 95% CI 1.04–1.90; aOR 1.29, 95% CI 1.01–1.64; and aOR 1.47, 95% CI 1.15–1.88)." (PMID 38186903, 2024). "CKD patients treated with insulin, PPI, diuretics, antiplatelets or immunosuppressants were at higher risk of severe COVID-19." (PMID 38186903, 2024). "Conversely, COVID-19 vaccination maintains homeostasis of insulin secretion by activating insulin receptors." (PMID 38609366, 2024). "While the specific mechanisms differ between the two types, COVID-19-induced disruptions in the insulin signalling pathway can be central to the development and propagation of both T1DM and T2DM." (PMID 38651404, 2024). "The link between long COVID-19 and insulin resistance sheds light on the diverse and often systemic consequences of SARS-CoV-2 infection, as seen in our study." (PMID 39338165, 2024). "Protein phosphatase 1 and regulatory subunit 1A (PPP1R1A), which is positively correlated with insulin impairment, were relatively stable in every group, except in one elder COVID-19 model in which these indexes were significantly elevated (599.9502 pg/mL)." (PMID 38609366, 2024). "Patients with a history of diabetes who later developed COVID-19 presented uncontrolled hyperglycemia and episodes of acute hyperglycemic crises that required exceptionally high insulin doses." (PMID 38397885, 2024). "In the early stages, some studies suggested that insulin treatment was prioritized over oral hypoglycemic drugs in treating patients with COVID-19 and T2DM." (PMID 38755442, 2024). "Both critical illness and SARS-CoV-2-related mechanisms such as an increase in IFN-γ and ACE2 downregulation impair insulin sensitivity in skeletal muscle during COVID-19." (PMID 37934800, 2024). "Among the antidiabetics, metformin, DPP4is and GLP-1Ras, SGLT2is, and insulin have been administered in patients with COVID-19." (PMID 36979949, 2023). "In the first seven days of admission, severe COVID-19 patients require more than two times the insulin doses they would normally require." (PMID 38192935, 2023). "Regarding COVID-19-related hospitalization, the most significant comparison was between insulin/insulin secretagogues and metformin (with an OR of 0.74 [95% CI 0.60–0.92]), indicating a lower risk associated with metformin use." (PMID 37626788, 2023). "In patients with moderate severity of COVID-19, average blood glucose was also significantly higher in the insulin-only treated group (197 ± 76 vs 168 ± 51 mg/dL, P = .001)." (PMID 36701712, 2023). "A recent observational study reported that the requirement for insulin is significantly higher among COVID-19 patients, thus attributing to beta-cell dysfunction induced by SARS-CoV-2 infection." (PMID 36839456, 2023). "Using medicines including ASA, Enoxaparin, Levothyroxine, and Insulin was significantly higher in COVID-19 group." (PMID 37543921, 2023). "The COVID-19 patients showed considerably greater fasting blood glucose, insulin, and insulin resistance levels than their controls." (PMID 36843827, 2023). "A small study showed that insulin infusion was beneficial in achieving glycemic targets, hence ensuring a better COVID-19 outcome; however, larger observational studies showed association with increased mortality." (PMID 37374918, 2023). "Higher plasma contents of creatine/creatinine can be an indication of lower sensitivity to insulin, as we observed in the fatal cases of COVID-19." (PMID 37512587, 2023). "Acute COVID-19 children exhibited elevated levels of C-peptide, Insulin and Glucagon in comparison to convalescent and control children." (PMID 37013538, 2023). "Patients with severe COVID-19 and DM frequently require higher doses of insulin, thereby multi-injection insulin therapy is considered the most appropriate therapeutic option." (PMID 36979949, 2023).